CD4 (CD4 molecule)
Diseases named in the same sentence as CD4 in open-access papers (continued):
Sharing a sentence is not in itself a finding about the gene and the disease.
tumor (continued). "We hypothesize that tumor-specific CD8+ T cell responses are largely derived from the periphery in NeoAg/ICB-based immunotherapies and can remain ignorant of CD4+ T cell specificity in a vaccine, as long as help is provided." (PMID 37655661, 2023). "Furthermore, tumor-infiltrated CD8+ T and CD4+ T cells in the allografts highly expressed the activation/exhaustion markers, such as GZMB, GZMK, PDCD1, LAG3, HAVCR2, and CTLA-4." (PMID 37980406, 2023). "The tumor may be suppressed through cellular immune mechanisms involving CD4+ T cells, CD8+ T cells, and NK cells, while CAF, as a major part of the tumor stroma, played a crucial function in tumor immune evasion." (PMID 38078879, 2023). "Other pre‐treatment biomarkers, including CD3+, CD8+, CD3 + CD4+, CD20+, CD68+ tumor‐associated macrophages (TAM), NK cells, and TLS, were not different between the TRG 1–3 and TRG 4–5 groups." (PMID 36341590, 2023). "However, CD4+ cells and CD8+ cells in patients with high expression of ICOSLGTCs at the tumor center showed a decreasing trend." (PMID 37842091, 2023). "Using multiplex IHC assays, we showed that FGFBP2+NKT cells (positive for CD8, NCAM1, and FGFBP2, but not for CD4) were mainly present in the para-tumor regions and were sparsely distributed in the tumor regions." (PMID 38065972, 2023). "Therefore, we used immunohistochemistry to evaluate the quantity and distribution of CD4+ lymphocytes, CD8+ lymphocytes, CD68+ macrophages, CD163+ macrophages, and M1-macrophages in the tumor center and invasion front in a cohort of 55 OSCC patients." (PMID 36836239, 2023). "Such treatment significantly increases cytokine secretion and the infiltration of functional CD4 + and CD8 + T cells, consequently turning “cold” tumour “hot”, showing remarkable growth inhibition to both primary tumour and distant tumours in two types of xenografts-bearing mice." (PMID 37019890, 2023). "Additionally, PD-L1 and LAG-3 combination therapy has shown synergistic effects on CD4+ and CD8+ T-cell cytokine production and tumour control." (PMID 37386922, 2023). "CD4+T cells (r = 0.429, p = 7.90e − 17), while neutrophils (r = 0.544, p = 5.24e − 28) and dendritic cells (r = 0.464, p = 1.40e − 19) were significantly increased in HCC, were negatively correlated with tumor purity (r = − 0.247, P = 1.40E − 19)." (PMID 37306737, 2023). "Both NK cells and CD8+ T cells are necessary for tumor cell killing and CD4+ T-cell activation was reduced without NK cells." (PMID 37923822, 2023). "Meanwhile, responders had increased percentages of tumor-infiltrating CD3+ and CD4+ T cells." (PMID 37446056, 2023). "This is likely due to differences in relative immune proportion in the tumor RNA-seq sample, as we observed TIL PD-L1 IHC was modestly correlated with RNA-estimated immune proportion (P = 0.0083, ⍴ = 0.18), CD4 expression (P = 0.00083, ⍴ = 0.22) and CD8 expression (P = 6.1e-5, ⍴ = 0.26)." (PMID 35881197, 2023). "The depletion of CD4+ T cells from SRIL, which control cell-mediated immunity against tumors and exert anti-tumor effects on CD8+ T cells, could influence the prognosis." (PMID 36923437, 2023). "For example, CTLA-4 expressed on tumor-infiltrating Treg cells (TI-Tregs) can bind to CD80/86 with higher affinity than CD28, impairing the maturation of APCs and costimulatory signals to further hinder the activation of anti-tumor CD4+ and CD8+ T cells." (PMID 39872303, 2023). "CD8+ T cells have traditionally been considered responsible for cytotoxicity, as even without CD4+ T cells MHC class I-restricted T cell receptor (TCR) transgenic mice maintained their anti-tumor activity." (PMID 39086686, 2023). "In this study, we compared differences in gene expression profiles between peripheral circulation and tumor tissue infiltrated CD4+ T cells, and analyzed the correlation between the level of CCR8 expression on CD4+ T cells from different sample sources and clinical characteristics." (PMID 37950246, 2023).
tumor (continued). "It was found that CRT-NP plus FUS (CFUS) upregulated the CRT expression, expanded the population of melanoma TRP-2 specific functional CD4+ and CD8+ T Cells and tumor-suppressing M1 phenotype macrophages, and increased the expression of PD-1 and PD-L1 in T Cells." (PMID 37180717, 2023). "Flow cytometry analysis of peripheral blood and tumor/paraneoplastic tissues from colorectal cancer (CRC) patients and healthy controls revealed the accumulation of LAP + CD4 + T cells in the tumor microenvironment, with immune evasion mediated by IL-10 and TGF-β promoting tumor metastasis." (PMID 37689664, 2023). "CTLs and CD4+ Th1 cells can secrete IFN-γ, which restricts the proliferation of ECs and induces their apoptosis, resulting in the restriction of blood flow in the tumor." (PMID 38193080, 2023). "The Raji tumor progression in all mice without CD4/CD8 cells indicates T cells are necessary for Raji tumor control in HIS mice." (PMID 37087494, 2023). "CD73 expression in tumor showed a significant negative correlation with CD4+ helper T cells and Plasma cells." (PMID 37392167, 2023). "Our results demonstrate that adoptively transferred TRP-1 CD4+ T cells can indirectly eradicate established tumours that evade CD8+ T cell control in the absence of NK cells." (PMID 37316667, 2023). "We analyzed tumor-infiltrating lymphocytes (TILs) by flow cytometry on day 7 post CAR T-vax treatment and observed substantially increased endogenous CD8+ TILs and a trend toward increased CD4+ cells." (PMID 37413990, 2023). "The tumor cells were reactive for T-cell markers (CD2, CD3, CD4, CD10)." (PMID 39092006, 2023). "Notably, DNAJB4 overexpression markedly enhanced CD4 + and CD8 + T cells and reduced PD-L1 levels in 4T1 tumors via the Hippo pathway, which retarded tumor growth in a subcutaneous xenograft tumor mouse model of 4T1 cells." (PMID 37548821, 2023). "Previously, we showed that a lack of CD4+ T helper type 1 (Th1) cells in the tumor at baseline, and their inability to cluster with CD8+ T-cells and myeloid cells upon treatment, were associated with resistance to pembrolizumab." (PMID 35976415, 2023). "Tumor antigens can be captured and processed by dendritic cells, which can be stimulated by Lipo-MP-LPS, as described for other TLR4 agonists, leading to the secondary activation of CD4 and CD8 T-cells in periphery." (PMID 37760603, 2023). "The induction of tumor antigen-specific CD8+ and CD4+ TRM cells prior to the seeding of tumor cells from the lungs by extra-pulmonary tumors is necessary to provide a potent immunocompetent environment to eliminate DTCs thereby preventing their outgrowth from becoming overt metastatic lesions." (PMID 36839766, 2023). "Although there was no change in the proportion of CD4+ T cells, the percentages of tumor-infiltrating CD3+ T cells, CD8+ T cells, IFN-γ+CD8+ effector T cells and B cells were significantly increased in G7 compared with those in G1, G4, and G6." (PMID 36959204, 2023). "However, research on CD4+ T cell differentiation and tumor regulation in LUAD tumor microenvironment is still insufficient." (PMID 37744350, 2023). "Consistent with the overall density of CD4 and CD8 T cells, densities of HLA-DR+ activated T-cell subsets, which are major producers of cytotoxic molecules and proinflammatory cytokines, were also lower within the tumor core of liver metastases." (PMID 37768208, 2023). "Additionally, there was a significant decrease in both CD4+ and CD8+ tumor-infiltrating lymphocytes (right)." (PMID 37092550, 2023). "Although cross-linking CD40 did achieve complete tumor regression in the absence of CD4+ T cells, it did occur at a slower kinetic rate compared to tumor-bearing animals having an intact CD4+ T cell population." (PMID 37655661, 2023).
tumor (continued). "Besides, immune cells including CD4 helper T cell subsets (Th1, Th2, and Th17) and B cells have been shown to display features of a double-edged sword in PDAC TME and play either tumor-suppressing or tumor-supporting roles in context-dependent manners." (PMID 37771596, 2023). "Although the role of CD26+CD8+ T cells in cancer models has not been investigated, polyfunctional CD4+CD26high T cells display markers of stemness/migration and elicit anti-tumor activity in different malignancies." (PMID 36707896, 2023). "Similar to tumor‐infiltrating CD8+ T cells, those CD39+CD4+ T cells also express TOX." (PMID 37829505, 2023). "Therefore, CD4+ T cell help is essential to prime CD8+ T cells by antigen cross‐presentation, even in MHC‐II‐negative tumor cells." (PMID 37829505, 2023). "The results indicated that the levels of SLC7A2 transcripts were positively correlated to the levels of macrophage, neutrophil and dendritic cell infiltrates in LUSC and to the tumor purity, B cell, CD8+ T cell, CD4+ T cell, macrophage, neutrophil and dendritic cell infiltrates in LUAD." (PMID 36639771, 2023). "Moreover, the frequencies of CD4+ and CD8+ T cells were significantly up-regulated in the tumor tissues, with substantial increases in IFNγ, TNFα and IL-17A expression in CD8+ T cells and augmented IL-17A expression in CD4+ T cells." (PMID 38074634, 2023). "TGF-β can significantly inhibit CTL activity and also promote tumor growth independent of CD4+ T cells, interferon (IFN)-γ, and CTLs." (PMID 38193080, 2023). "The MC38 tumor-bearing mouse model also confirmed that PD-1 expression was up-regulated in CD4+ and CD8+T cells in the non-ablated tumors after MWA treatment." (PMID 36900218, 2023). "In addition, CEB induced the tumor microenvironment remodeling as indicated by the increase of CD8 + and CD4 + T cells, as well as a decrease of M2 TAM and Myeloid-derived suppressor cells (MDSCs)." (PMID 36759822, 2023). "KSQ-001 consisted of CD3+ cells with no detectable residual tumor cells, with patient-unique frequency of CD4+ and CD8+ T cells not affected by inactivation of SOCS1." (PMID 38099496, 2023). "Among them, CD4+ and CD8+ T lymphocytes play a crucial role in improving anti-tumor immunity." (PMID 37197434, 2023). "Oral supplementation of A. muciniphila restored the efficacy of PD-1 blockade in mice in a white blood cell-dependent manner by increasing the recruitment of CCR9+ CXCR3+ CD4+ T lymphocytes to the mouse tumor bed after FMT using nonresponder feces." (PMID 37691931, 2023). "Interestingly, when comparing bladder tissue and tumor samples, increased levels of LAG3 were seen in CD4+ lymphocytes, CD8 and CD127 in CD8+ lymphocytes, as well as SIRP within the monocyte population was found in the bladder." (PMID 36900156, 2023). "Furthermore, we found that CD4+ CTLs expressed C-X-C motif chemokine ligand 13 (CXCL13), a B cell chemoattractant, and physically interacted with activated B cells in tumor lesions." (PMID 38077321, 2023). "Recent data have shown that MDSCs are the chief controllers of cancer immune responses and inflammation in individuals with tumours as they intensely constrain the antitumor immune response of CD4+ T cells, CD8+ T cells and NK cells, thus triggering tumour growth." (PMID 36817434, 2023). "To characterize the activation of cytotoxic CD4+ and CD8+ T cells, the main cellular mediators of the anti-tumor immunity, we first assayed the expression of the immune checkpoints PD-1, LAG-3, and TIM-3, known to reflect the immune status of TILs in solid tumors." (PMID 36854895, 2023). "Stimulated CD4+ and CD8+ T lymphocytes may respond to immunogenic signals, such as pro-inflammatory cytokines, which are released from dead tumor or immune cells." (PMID 37111629, 2023).
tumor (continued). "The mechanism of action was that the vaccine promoted the expression of the surface molecules CD40, CD80, and CD86 of DCs, allowing DCs to efficiently present antigens to T cells, enhancing the proliferation and activation of CD4+ and CD8+ T cells in mice and delaying tumor growth." (PMID 37876967, 2023). "Accordingly, the increased CD4+ and CD8+ T cells, Th1, and IFN-γ production in the liposomal combination therapy group in the present study showed the greater efficacy of this method in tumor suppression." (PMID 37037839, 2023). "Recent years, anti-tumor therapeutic vaccines have been developed as an active strategy to specifically recognize and destroy malignant cells by inducing CTL responses and CD3+CD4+ T helper cell activation relying on tumor antigens." (PMID 37208748, 2023). "Cluster A is an immunosuppressive phenotype, showing reduced infiltration of anti-tumor immune cells such as CD8 + T cells, CD4 + T cells and NK cells, and increased activity of energy metabolic pathways such as ROS pathway, glycolytic and mTORC1 signaling pathways." (PMID 37024911, 2023). "Immunohistochemical staining for CD4+ and CD8+ T cells showed remarkably increased numbers of CD4+ and CD8+T cells infiltrating into the tumor tissues in mice treated with the combination of B. longum 420 and anti-PD-1 and anti-CTLA-4 antibodies compared to the other treatment groups." (PMID 37340017, 2023). "Regarding immunosuppressive cells in tumor-bearing CD1d−/− mice, WTMCGEP did not influence the abundance of tumor-infiltrating CD4+ and Forkhead box protein 3+ regulatory T cells." (PMID 37152373, 2023). "We found that CD70-KO in C666 cells greatly enhanced cytotoxicity-dependent tumor cell death, preferentially in a co-culture system similar to the physiological T-cell landscape in NPC patients, with a higher expression of CD27 on CD4+ T cells." (PMID 37024479, 2023). "In addition, transferring IL-21-expressing CD4 T cells into B16F10 tumor-bearing mice enhanced the proliferation of CX3C chemokine receptor 1+ CD8 TILs, which correlated with improved tumor control." (PMID 37409128, 2023). "In summary, the stimulatory interaction and immune checkpoint modulation between malignant cells and CD4+ Tregs may account for activated Tregs infiltration in the high KIF18B expression group, promoting tumor growth and progression." (PMID 37744335, 2023). "By simultaneously depleting the glutathione (GSH) and boosting HIFU-induced tumor ICD, MBPs can modulate the tumor immune microenvironment by inducing dendritic cell (DC) maturation and promoting CD8+ and CD4+ T cell activation, thereby inhibiting tumor growth and lung metastasis." (PMID 37242696, 2023). "This may reflect an increased expression of A2AR on Treg cells, which are known to express high levels of CD39 and PD-1 in the tumor microenvironment, particularly given CD4+GFP+CD39+ cells were enriched for CD25+ cells relative to CD4+GFP+CD39− counterparts." (PMID 37914685, 2023). "To evaluate whether CD4 depletion impacted tumor-specific CD103+ CD8 T cell formation, we examined T cells in the tumor environment." (PMID 37072485, 2023). "In addition, many studies showed that Tregs in tumors can inhibit the proliferation of autologous CD4 and CD8 T cells [++25] and that the frequency of Tregs is negatively correlated with the expression of interferon (IFN)-γ and IL-2 in tumor tissues." (PMID 36755298, 2023). "RUNX3 is an important mediator during lymphocyte differentiation into CD4+ and CD8+ cytotoxic T -lymphocytes (CTL) and natural killer cell progenitors into natural killer (NK) cells, and is thus likely pivotal in the development of anti-tumor immunity." (PMID 36900240, 2023). "Furthermore, chemo-photothermal therapy-induced ICD increased TME immunogenicity and T cell activation, significantly boosting the number of CD4+ (30.9%) and CD8+ (31.3%) T cells at the tumor site." (PMID 36987269, 2023).
tumor (continued). "Interestingly, vaccination also markedly enhanced tumor infiltrating CD8+ T cells and boosted both the central memory (TCM) and effector memory (TEM) CD8+ T cell frequencies and function in CD4+ and CD8+ T cell subsets." (PMID 36875137, 2023). "The abundance of cell-cell interactions in Mast cells, CD4 T cells, S100A8+ macrophage, and tumor cells compared to other cells was higher in responders than in non-responders, which indicated that there was more communication between these cell types in the responders." (PMID 37152010, 2023). "Notably, CD4+ CAR T cells can exert potent antitumor activity (and even outperform CD8+ CAR T cells) in certain preclinical tumor models." (PMID 37248395, 2023). "Furthermore, in vivo depletion of CD4+ and CD8+ T cells in immune competent mice reduced overall survival of a-TEA-treated, tumor-bearing animals implicating T cells in the anti-tumor immune response." (PMID 36911733, 2023). "Our analysis on immune cell subsets from separated tumor tissues showed high expressions of CCR8 on Treg cells in control T and CAR-T groups, oxamate treatment reduced CCR8 expressions, while elevated IL-17 A expressions in CD4 + T cells." (PMID 37770937, 2023). "The differentiation of CD4+ T cells to CTL relies on constant antigen presentation, whether from a virus or a tumor, and ceases once the antigen level is reduced." (PMID 37965314, 2023). "In detail, CD8+ TILs have been shown to directly kill tumor cells when presented with neoantigens and are also capable of activating apoptosis-inducing FAS–FASL pathways; CD4+ T cells play a regulatory role by differentiating into different phenotypes, such as Th1, Th2, Th17 and Treg." (PMID 36831480, 2023). "Given our observation of increased in number and activity of tumour-infiltrating CD8+ and CD4+ T cells in response to combined inhibitor treatment, we reasoned that the T cells might be central to the anti-tumour efficacy of combined inhibitor treatment." (PMID 37582853, 2023). "Already at the early stage of tumor growth examined here by scRNA-seq, we observed a strong trend for reduced CD8+ T cell infiltration in βA compared to Ctrl tumors, whereas the number of CD4+ T cells was unchanged." (PMID 38304252, 2023). "This happened despite lack of MHC II expression on tumour cells, indicating that CD4+ T cells recognised tumour antigens that were phagocytosed and presented by professional APCs." (PMID 37386922, 2023). "Furthermore, RUNX3 is an important mediator during the development of both CD4+ and CD8+ cytotoxic T-lymphocytes (CTL), and is thus likely pivotal in the development of anti-tumor immunity." (PMID 36900240, 2023). "Then, the killing abilities of CD4+ and CD8+ T cells on target 4T1 tumor cells were studied." (PMID 37108179, 2023). "Bregs are important immunosuppressive cells in the OC TME; they produce IL-10 and TGFβ, express several immune checkpoints at their surface (PD1, PDL1, OX40 etc) to impair CD4+ and CD8+ T cell proliferation and can promote tumor growth and progression via IL-35 signaling." (PMID 38164130, 2023). "Glucocorticoids likely act at multiple levels to inhibit T cell antitumor immunity, including suppression of antigen-presenting cells, macrophages, and CD4+ helper and CD8+ effector T cells, and we indeed found that both CD4+ and CD8+ T cells are signaled by tumor-derived glucocorticoids." (PMID 37471141, 2023). "Additionally, TRIM28 expression was positively related to tumor purity and the presence of CD8+ T cells, CD4+ T cells, macrophages, neutrophils, and dendritic cells in GBM and LIHC (all p values < 0.001)." (PMID 37781084, 2023). "Both CD4 and CD8 T cells were able to kill HT-29 tumor cells." (PMID 37185301, 2023). "The authors hypothesize that tobacco smoking-generated inflammation polarizes CD4+ CM and CD4+ EM cells that may contribute to the exacerbation of COPD and impairment of tumor-protective immunity in NSCLC." (PMID 38187374, 2023).